ENSG00000201619
Synonyms: LOC124900429
Gene: Small nucleolar RNA gene on chromosome 1 (179,201,487 to 179,201,627, forward strand). Ensembl gene ENSG00000201619.
Gene Ontology:
Biological process: RNA processing
Cellular component: nucleolus
Homologues: Paralogues in human: SNORA67 (90% identical).